BDNF (brain derived neurotrophic factor)
Diseases named in the same sentence as BDNF in open-access papers (continued):
Sharing a sentence is not in itself a finding about the gene and the disease.
depression (continued). "By diminishing neuronal plasticity, a change in factors as BDNF levels might thus impel depression." (PMID 31127089, 2019). "Thus, Pyk2 could be included in the list of molecules known as negative modulators of resilience-like phenotypes against chronic stress and depression, such as BDNF and ΔFOSB30." (PMID 30664624, 2019). "Some studies demonstrated that single nucleotide polymorphism Val66Met in the BDNF gene was associated with decreased hippocampal volume in persons with major depressive disorder (MMD) and may contribute to a genetic predisposition for depression." (PMID 31234814, 2019). "Dysregulation of miRNAs is associated with depression, hence miRNAs may be useful therapeutic targets and are indeed targets of effective antidepressants; the SSRI, fluoxetine decreases levels of miR-16 (regulates BDNF) in mouse hippocampus." (PMID 31442236, 2019). "Therefore, the present study aimed at investigating whether there is a difference between the two tDCS protocols in changing BDNF serum level and reducing the level of depression signs, anxiety, stress, and craving for drugs among opioid-taking patients." (PMID 32477481, 2019). "Moreover, BDNF treatment reduced anxiety‐like and depression‐like behaviors." (PMID 30585393, 2019). "We speculate that the high inflammatory factor levels in the hippocampus will decrease BDNF/TrkB expression to develop the depression, but in the spinal cord and DRG, the high inflammatory factor levels will increase BDNF/TrkB expression to facilitate the transmission of pain." (PMID 31601968, 2019). "Similarly, the overall area under the curve of receiver operating characteristic was 0.82, indicating the highly conserving of serum BDNF levels as an biomarker for screening of depression in young adults with acne vulgaris (72% sensitivity and 85% specificity)." (PMID 31234814, 2019). "The proposed mechanisms for the antidepressant action of exercise are predominantly connected to increased BDNF content in the hippocampus that may account for enhanced neurogenesis and diminished clinical manifestations of depression, with a significant role of β-endorphins." (PMID 30792631, 2019). "A decrease in BDNF may lead to brain dysfunction and induce depression." (PMID 32009949, 2019). "Various evidence supported the hypothesis that BDNF is involved in the etiology of depression." (PMID 31193084, 2019). "In addition, similar to the present results, the results from an assay showed that MS could trigger the depression-like behavior accompanied with downregulated CREB/BDNF expression and mRNA level of BDNF." (PMID 30984042, 2019). "Thus, proBDNF in the hippocampus may have different biological functions in anxiety/depression than mature BDNF." (PMID 30740068, 2018). "Accordingly, we have recently shown that in the basal conditions the protein levels of the BDNF and trkB, in the hippocampus of the RLA rats, are lower than those of their RHA counterparts, consistent with the susceptibility of the RLA line to stress-induced depression." (PMID 30477252, 2018). "Since the analysis of the set of basic genes associated with the neurotrophic theory of depression did not provide any conclusive feedback, the next step was to determine the expression of three neurotrophic factors, BDNF, NGF, and NTF3, on the protein level assessed by Western blot." (PMID 30294251, 2018). "Thus, the exercise intensity may have a critical role for initiating/restoring optimal neuroplasticity, which is mediated by BDNF, such as in major depression, a psychiatric state which can be influenced by tDCS and AE." (PMID 30687048, 2018). "It is worthy to speculate whether B2M impairs neurogenesis and induces depressive- and anxiety-like behaviors are relate to inhibiting the expression of BDNF and exogenous giving BDNF can reverse the toxicity of B2M in neuroprotective depression and anxiety disease?" (PMID 29795686, 2018).
depression (continued). "The present results confirmed our previous finding that in the basal conditions, the protein levels of BDNF and trkB, in the hippocampus of RLA rats, are lower than those of their RHA counterparts, consistent with the susceptibility of the RLA line to stress-induced depression." (PMID 30477252, 2018). "Thus, there might be an etiological link between altered BDNF and impaired neuroplasticity in depression." (PMID 30367065, 2018). "Stress causes reduction of brain derived neurotrophic factor (BDNF) expression and the mechanistic target of rapamycin (mTOR) in synapse, consequently contributing to the loss and atrophy of specific synapse in the brain regions implicated in depression, particularly the PFC and the hippocampus." (PMID 29896088, 2018). "Indeed, in humans, it was shown that plasma levels of BDNF are decreased in depression but that downregulation of BDNF in the brain structures was restricted to the hippocampus and prefrontal cortex (PFC), while BDNF levels were increased in the nucleus accumbens and amygdala." (PMID 30294251, 2018). "Therefore, studying whether FGF-2 affects the expression and activity of BDNF as an indicator of depression would be interesting." (PMID 30369869, 2018). "Thus, control of hippocampal BDNF is an important target for the treatment of depression." (PMID 29643431, 2018). "Evidence suggests that, the levels of BDNF were decreased in the models of depression and anxiety, exogenous giving BDNF could ameliorate the depressive- and anxiety-like behaviors, and knockout the expression of BDNF could induce depressive- and anxiety-like behaviors in animals." (PMID 29795686, 2018). "To investigate the association between BDNF Val66Met polymorphism (rs6265) and emotional symptoms in mTBI patients, we recruited 192 mTBI patients and evaluated their Beck Anxiety Inventory (BAI) and Beck Depression Inventory (BDI) scores in the first and sixth week after mTBI." (PMID 29357818, 2018). "In addition to reduction in depressive symptoms, we were interested in exploring if exercise reduces the residual symptoms of depression, notably cognition and sleep quality, and identifying putative biochemical biomarkers (such as BDNF, cytokines, and CTHB) related to treatment response." (PMID 29559928, 2018). "As such, elevated levels of BDNF in the regions within the orbital and medial prefrontal cortices, which can integrate sensory information and increase the outgrowth of neurites and the neuroplasticity, may decrease depression." (PMID 30224933, 2018). "The emerging hypothesis that genetic alterations predisposes individuals to vulnerability under stressful conditions is well supported by the results that heterozygous BDNF Val66Met mice display anxiety- and depression-like behavior phenotypes only after exposure to a paradigm of sub-chronic stress." (PMID 30347685, 2018). "The proposed sequence of events triggered by ketamine in depression involves blocking of NMDAR on gamma-aminobutyric acid- (GABA-) ergic interneurons in the prefrontal cortex, which causes disinhibition and increases glutamate release, which primarily excites AMPAR, leading to activation of BDNF." (PMID 28299207, 2017). "The relationship among BDNF, sleep and depression has been speculated." (PMID 29299044, 2017). "Therefore, the BDNF could become a new target for treating chronic pain-induced depression in the near future." (PMID 28706741, 2017). "It has been shown that PA increases BDNF in unmedicated patients with MDD and elderly persons with remitted depression." (PMID 28928987, 2017). "Thus, the findings imply that the ApoE4-mediated increased risk of developing depression could be partially attributed to the upregulation of 5-HT2A and downregulation of BDNF signaling in ApoE4 carriers compared with carriers of the other two isoforms." (PMID 28934977, 2017).
depression (continued). "Nonetheless, the robust correlation between depression and Impacts score has been previously acknowledged, giving way to the proposition that irisin may serve as a link between altered irisin/BDNF path and evolution of distress disorder." (PMID 29217995, 2017). "And a decreased serum BDNF level may be an indicator of vulnerability to develop depression." (PMID 28118829, 2017). "Thus, the BDNF hypothesis in depression, postulates that stress reduces the concentration of BDNF in structures of the limbic system, responsible for the emotions." (PMID 29299044, 2017). "Also, most of these studies report that PA increases neurogenesis in the hippocampus, reduces the length of corticosteroid exposure following stress, improves circadian rhythmicity, increases synaptic plasticity gene activity, and increases hippocampal BDNF in models of depression." (PMID 28529805, 2017). "Indeed, antidepressant treatment increases BDNF levels, stimulates neurogenesis and reverses the inhibitory effects of stress, while infusions of BDNF into the hippocampus have antidepressant properties in rodent models of depression." (PMID 35098038, 2017). "Therefore, it is postulated that BDNF plays an essential role in the pathophysiology of depression." (PMID 27975125, 2017). "An increased vulnerability to depression-like behaviors was observed in BDNF-heterozygous knockout mice, while human studies have reported that the presence of the BDNF Val66Met allele blocks the normal maturation of BDNF and may cause neuronal atrophy in hippocampal neurons." (PMID 28446154, 2017). "However, increased levels of BDNF were found in some depression studies." (PMID 29348904, 2017). "Brain-derived neurotrophic factor levels can be influenced by various factors commonly found among substance users such as smoking, alcoholic consumption, and various neuropsychiatry disorder, which includes depression, anxiety, bipolar disorder, and schizophrenia." (PMID 29164087, 2017). "Several depression-like behaviors were observed in social isolation mice, including decreased relative sucrose preference, longer immobility time in forced swimming test, lower plasma corticosterone and decreased brain-derived neurotrophic factor in hippocampus." (PMID 28052034, 2017). "Importantly, animal models of depression have demonstrated that reduced levels in both BDNF expression and hippocampal neurogenesis occurs along with depressive behaviors, suggesting that a changed status of the BDNF/TrkB system and reduced neurogenesis are associated with depressive symptoms." (PMID 29099059, 2017). "However, presumed elevated BDNF levels among individuals with the Val/Val genotype, might confer increased responsivity to contextual challenges, thus fostering vulnerability to depression." (PMID 28769852, 2017). "It has been speculating the relationship between BDNF, sleep and depression." (PMID 29299044, 2017). "Interestingly, blood and hippocampal BDNF levels are reduced in patients with depression." (PMID 28872625, 2017). "Therefore, we wondered whether spinal GRs participate in the influence of depression on neuropathic pain by regulating BDNF expression and related signaling pathways." (PMID 28579944, 2017). "More specifically, exposure to corticosterone decreases BDNF expression in the brain; this suggests a negative relationship between cortisol and BDNF, which alters mood and may cause depression." (PMID 29312105, 2017). "In contrast to the effects seen in the hippocampus, infusion of BDNF to the ventral tegmental/nucleus accumbens area increased depression-like behavior (shorter latency to immobility in the forced swim test) through mechanisms that may involve maladaptive learning." (PMID 28928987, 2017). "Thus, PA may protect against stress-induced depression by altering kynurenine metabolism and, thereby, modulating BDNF levels." (PMID 28529805, 2017).
depression (continued). "Additionally, the BDNF Val66Met polymorphism, which leads to reductions in proBDNF (the precursor to active BDNF), is a predictor of major depressive disorder in male humans but not in females." (PMID 28638713, 2017). "It suggested that SCE could improve the depression-like emotional status and associated cognitive deficits in CUMS mice, which might be mediated by regulation of BDNF levels in hippocampus, as well as up-regulating of TrkB/CREB/ERK and PI3K/AKT/GSK-3β pathways." (PMID 28761074, 2017). "Furthermore, the neurotrophic hypothesis of depression postulates that compromised neurotrophin brain-derived neurotrophic factor (BDNF) function is directly involved in the pathophysiology of depression." (PMID 29348904, 2017). "Therefore, factors such as depression, smoking, and alcohol intake should be taken into consideration as these could affect the BDNF levels and contribute to contrasting findings." (PMID 29109736, 2017). "In addition, we found that the BDNF/proBDNF ratio was decreased in depression, which is consistent with two previous studies, indicating that the imbalance or the insufficient conversion of proBDNF to BDNF might have a role in major depression." (PMID 28375203, 2017). "Likewise, there is evidence for a role of BDNF in depressive disorders as serum concentrations of this neurotrophin may be diminished among depressed individuals relative to controls." (PMID 28769852, 2017). "While our study’s findings are not in accordance with the hypothesis that lower levels of BDNF are associated with depression and suicidal behaviour, they are consistent with other studies of this relationship." (PMID 27121496, 2016). "Since the BDNF hypothesis of depression postulates that a reduction in BDNF is directly involved in the pathophysiology of depression, we evaluated the anti-depressive effects of HMF in mice with subcutaneously administered corticosterone at a dose of 20 mg/kg/day for 25 days." (PMID 27120588, 2016). "Accumulating preclinical and clinical studies have suggested that the brain-derived neurotrophic factor (BDNF) plays an important role in the pathophysiology of MDD and serum levels of BDNF may have the relationship with clinical responses to treatments for depression." (PMID 27777607, 2016). "Indeed, numerous studies have shown reduced serum levels of brain-derived neurotrophic factor (BDNF) in patients with MD compared to healthy controls, and evidence also exists to support renormalization of BDNF levels upon successful anti-depression interventions." (PMID 28082989, 2016). "Thus, we hypothesized that susceptibility to CS exposure exists during prenatal and early postnatal periods and that CS exposure during these “critical periods” may alter BDNF/TrkB signaling and induce depression-like behaviors in later life." (PMID 26503133, 2016). "We for the first time report that KOR activation causes changes in BDNF and Rac1 expression, which are considered as neurobiological markers of depression, but hippocampal level of these markers do not match with behavioral response to antidepressants in this model." (PMID 27634008, 2016). "While studies of depression support the hypothesis that increases in inflammation result in decreased BDNF and attenuated neuroplasticity, we report decreases in both peripheral BDNF and inflammatory factors (although there is a trend for elevated IL-6 in CSS F2 females)." (PMID 34055816, 2016). "Therefore, we hypothesize that depression might trigger a mechanistic role for BDNF in cancer progression." (PMID 27852063, 2016). "The BDNF hypothesis of depression was recently proposed based on these findings." (PMID 27120588, 2016). "However, findings from clinical trials do not provide support for the notion that the BDNF polymorphism is suitable to predict the efficacy of tDCS as a treatment of depression." (PMID 28066217, 2016).
depression (continued). "Therefore, BDNF promoter methylation might independently contribute to the etiology and maintenance of depression, AUDs, and suicidal behavior in men, and it may mediate the effects of methylation on endocrine system receptors and signaling." (PMID 28096796, 2016). "Interestingly, several studies described BDNF as a marker for changes in different social behaviors, such as depression and anxiety, which could also impact maternal behavior." (PMID 27445727, 2016). "Therefore, the high levels of PAI-1 might inhibit the tPA/plasminogen system and inhibit cleavage of proBDNF, resulting in impaired BDNF signalling, which could result in reduced neural plasticity in the medial prefrontal cortex circuits in depression." (PMID 27456456, 2016). "Furthermore, impaired neuronal plasticity induced by low level of BDNF could lead to lower responses to antidepressants and lower remission rates, resulting in delayed recovery from depression." (PMID 25821488, 2015). "Thus, fluctuations in serum levels of BDNF and S100B seem to be state markers for major depression." (PMID 26500502, 2015). "Therefore, MEK, ERK1/2, CREB, and BDNF may compose a signal loop and play critical roles in the neural plasticity and etiology and treatment of depression." (PMID 25821488, 2015). "Additionally, peripheral BDNF levels increased after a successful treatment of an index manic episode but not of a depressive episode – although it should be noted that, in general, treatments for mania are more robustly efficacious than for depression." (PMID 26621529, 2015). "From these previous studies, serum BDNF levels may reflect a depression-related biological change." (PMID 25885038, 2015). "Therefore, given the apparently close relationship between Arc and BDNF, it is plausible to expect that Arc expression may also be altered in depression, and respond to antidepressant treatments." (PMID 26321903, 2015). "Findings about the association between BDNF levels and severity of depression are not ubiquitous." (PMID 26010085, 2015). "However, it is important to note that changes in serum BDNF and pro-BDNF during the trial were inversely correlated with depression severity at follow-up in the whole sample, although we do not understand the precise mechanism involved in the post-supplementation elevation in serum BDNF." (PMID 26151924, 2015). "Previous GxE studies suggested combined effects of 5-HTTLPR, a polymorphism in BDNF, and life stress on HPA activity and depression such as, and a recent review suggested complementary effects of these polymorphisms on the development and chronicity of depression." (PMID 25995833, 2015). "Finally, we investigated the protein interactome of BDNF and applied pathway-based analysis to examine the enrichment of biological pathways involved with BDNF in major depressive disorder (MDD) and bipolar disorder (BPD) separately, using two large GWA datasets." (PMID 26091093, 2015). "Thus, BDNF and cortisol may possibly explain the link between depression and glycated hemoglobin (HbA1c), insulin resistance, LDL and HDL." (PMID 26231223, 2015). "In this randomized double-blind controlled trial of severely injured patients vulnerable to posttraumatic stress disorder (PTSD) and depression, we examined whether DHA increases serum BDNF levels and whether changes in BDNF levels are associated with subsequent symptoms of PTSD and depression." (PMID 26151924, 2015). "Plasma BDNF levels have been found to predict disease outcomes of MDD patients, and findings from our study suggest BDNF hypermethylation in prevalent and chronic depression." (PMID 26285129, 2015). "Furthermore, BDNF and/or other neurotrophic factors may be reduced in disorders such as depression, as has been proposed due to the presence of reduced hippocampal volume in depressed patients." (PMID 25932008, 2015).